WNT5A (Wnt family member 5A)
Diseases named in the same sentence as WNT5A in open-access papers (continued):
Sharing a sentence is not in itself a finding about the gene and the disease.
colon carcinoma (continued). "WNT5A is down-regulated in a majority of colon cancers and suppressed during colon cancer metastasis." (PMID 34017835, 2021). "Another study showed that Wnt5a expression stimulated the directional migration and invasion of colon cancer cells and was correlated with poor prognoses." (PMID 32650388, 2020). "On the contrary, other studies demonstrated that Wnt5a was upregulated consistently in intestinal polyps and tumor samples, and increased Wnt5a expression predicted the early recurrence or metastasis in colon cancer patients." (PMID 32923386, 2020). "Colon cancer research has determined that Wnt5a/PKCα-dependent phosphorylation of serine residue 35 of RORα is crucial to link RORα to Wnt/β-catenin signaling." (PMID 33336001, 2020). "Contrastingly, in Sprague–Dawley rats, genistein (140 mg/kg) was found to decrease cell proliferation and induce the apoptosis of colon cancer cells through promoter hypermethylation and inactivation of the Wnt signaling activators, Sfrp2, Sfrp5, and Wnt5a." (PMID 32878338, 2020). "In order to investigate the role of Wnt5a/b in colon cancer, a TCGA colon cancer mRNA data set56 was used to compare Wnt expression levels in normal colon/rectum and adenocarcinoma tissue." (PMID 29453334, 2018). "We further demonstrate that Wnt5a/b is required for proliferation and viability of colon cancer cells via a β-catenin-independent signaling pathway." (PMID 29453334, 2018). "Next, we sought to determine the effect of administering different Wnt5a mRNA isoforms on colon carcinoma multicellular spheroid cultured cells in vitro." (PMID 28859077, 2017). "A similar tumor suppressive role of WNT5A has also been suggested in colon cancer and prostate cancer." (PMID 29069720, 2017). "In colon cancer, where WNT5A acts as a tumor suppressor, WNT5A restoration has been shown to inhibit EMT by antagonizing the Wnt/β-catenin signaling pathway." (PMID 27623766, 2016). "A number of studies have shown that the expression of miR-101b is significantly decreased in multiple types of cancer, such as colon cancer, in which, as previously noted, Wnt-5a levels are increased." (PMID 26895946, 2016). "In intestinal cancer, enhanced stromal Wnt5a expression in mouse intestinal tumors promoted adhesion sites to form focally and stimulated directional migration and invasion of colon cancer cells." (PMID 27571105, 2016). "In contrast, however, another study showed that Wnt5a expression stimulated directional migration and invasion of colon cancer cells and was correlated with poor prognosis." (PMID 27571105, 2016). "Further research is needed clarify this apparent discrepancy about the role of Wnt5a signaling in colon cancer." (PMID 27571105, 2016). "In various colon cancer cell lines, WNT5a expression was inversely correlated with promoter methylation." (PMID 25322458, 2014). "Our results nonetheless do not rule out a role for WNT5A in colon cancer through the canonical Wnt signalling pathway; indeed, WNT5A inhibits β-catenin/TCF-dependent transcription in HCT116 colon cancer cells." (PMID 20591152, 2010). "In contrast, up-regulation and down-regulation of Wnt5a are observed in gastric and colon cancer, as well as in cancer progression." (PMID 19300477, 2009). "To address this question, we investigated whether and how WNT5A signaling can interfere with cell surface molecules of colon cancer cells that are known to participate in the regulation of WNT/β-catenin-dependent signaling." (PMID 37998393, 2023). "The data from this public database confirm the overall survival findings showing that patients with high WNT5A mRNA expression in their colon cancer tissues have a significantly better five-year overall survival rate than patients with low WNT5A mRNA expression in their colon cancer tissues." (PMID 37998393, 2023).
colon carcinoma (continued). "In colon cancer, the WNT5A molecule has been predominantly defined as a cancer suppressor based on findings that patients with low WNT5A expression in their colon cancer tissue had a poor prognosis and the ability of WNT5A signaling to counteract essential cancer-promoting activities." (PMID 37998393, 2023). "Similarly, WNT5A regulates cellular migration and invasion in various types of colon cancers with a dependency on ROR2 function." (PMID 37722040, 2023). "In contrast, Elvira asserts that high WNT5A expression could induce colon cancer cell migration and invasion." (PMID 35155186, 2021). "However, another study using SW1116 colon cancer cells showed that genistein (75 μmol/L) treatment for 4 days inhibited cell proliferation by decreasing Wnt5a CpG island methylation and upregulating its expression." (PMID 32878338, 2020). "In cancers where canonical Wnt signalling is a key driver of the disease (eg through mutations in β-catenin or APC), such as colon cancer, ROR2 may play a major role in inhibiting the canonical pathway through binding to Wnt5a." (PMID 32807831, 2020). "Additionally, we found that these genes are regulated by auto- and paracrine Wnt5a/b secretion in colon cancer cells." (PMID 29453334, 2018). "However, we showed that proliferation of colon cancer cells depends on Wnt5a/b independent from the canonical Wnt pathway." (PMID 29453334, 2018). "Moreover, Wnt5a inhibited β-catenin target gene expression in colon cancer cells via PKC-induced Rorα phosphorylation." (PMID 27608847, 2016). "As ROR2 is reported to mediate the WNT5A-dependent inhibition of β-catenin-TCF-regulated genes in human embryonic cells, we tested whether WNT5A mediated the canonical Wnt-dependent role of aberrant epigenetic ROR2 repression in colon cancer." (PMID 20591152, 2010). "Previous studies demonstrated that EZH2 could silence the expression of WNT5A in colon cancer." (PMID 38566211, 2024). "Therefore, our results reveal that upregulation of FOXM1 by H3K79me2 in pancreatic cancer and colon cancer significantly inhibits maturation phenotypes and function of BMDCs through the Wnt5a signaling pathway, and thus provide novel insights into FOXM1‐based antitumor immunotherapy." (PMID 30628173, 2019). "We next asked whether Wnt5a/b is required for proliferation of colon cancer cells." (PMID 29453334, 2018). "Furthermore, transfecting colon cancer cells with Wnt5a led to downregulation of transcription factors considered key regulators of EMT, such as Twist and Zinc finger E-box-binding homeobox 1 (ZEB1), and induction of an epithelial phenotype by enhancing the expression of E-cadherin." (PMID 27571105, 2016). "Furthermore, silencing WNT5A in the highly invasive human colon cancer cell line may contribute to transcriptional regulation by histone modification." (PMID 24944588, 2014). "Another study on genistein showed that it inhibits CpG island methylation in the Wnt5a promoter region in colon cancer cell lines (DLD-1, SW480, and SW1116), resulting in elevated Wnt5a expression." (PMID 40239010, 2025). "To validate our WNT5A and LGR5 survival results, we assessed data for 274 patients from the colon cancer cohort TCGA-COAD who provided colon cancer tissue mRNA samples." (PMID 37998393, 2023). "Next, we investigated the predictive value of combining the mRNA expression levels (low and high) of WNT5A and LGR5 in colon cancer tissues and then correlated them with the overall survival of the patients." (PMID 37998393, 2023). "To investigate such a possible mechanism, we started by assessing the correlation between WNT5A and LGR5 expression levels in one and the same colon cancer patient cohort." (PMID 37998393, 2023). "Next, we investigated how WNT5A and LGR5 protein expression levels in colon cancer tissue were related to the overall survival of patients." (PMID 37998393, 2023).
colon carcinoma (continued). "The results regarding WNT5A signaling, LGR5 expression and the growth of colon cancer cells are in line with the role of LGR5 in promoting β-catenin-dependent signaling." (PMID 37998393, 2023). "Next, we investigated the predictive value of combining the mRNA expression levels (low and high) of WNT5A and DCLK1 in colon cancer tissues and then correlated the expression profiles with the overall survival of the patients." (PMID 37998393, 2023). "We have shown that recombinant WNT5A and/or Foxy5 can significantly inhibit WNT/β-catenin-dependent signaling in colon cancer cells in vitro as well as in vivo." (PMID 37998393, 2023). "By regulating the expression of transcription factor c-myc and Wnt5a, BRD4 is ascribed as a key determinant in acute myeloid leukemia (AML), multiple myeloma, Burkitt’s lymphoma, colon cancer, and inflammatory diseases." (PMID 35987950, 2022). "We found that the expression levels of some genes enriched in IL-11+ fibroblasts, including Wnt5a, Mmp13, Timp1, Il1rl1, Cxcl5, Saa3, Inhiba, Ascl4, and Tnfrsf11b, were elevated in mouse AOM/DSS-induced colon tumor tissues." (PMID 33863879, 2021). "IHC also confirmed that IL-11+ fibroblasts expressed Wnt5a in colons affected by DSS-induced colitis and colon tumor tissues from AOM/DSS-treated mice." (PMID 33863879, 2021). "Increased expression of WNT5a has been shown to promote EMT and metastasis in pancreatic cancer cells, while inhibiting EMT, cell proliferation and invasion in colon cancer." (PMID 25322458, 2014). "Indeed, the ROR2 extracellular ligand WNT5A, which inhibits the canonical Wnt signalling pathway in certain molecular contexts, is also aberrantly repressed by promoter hypermethylation in acute lymphoblastic leukaemia and in colon cancer, and its absence is tumourigenic in these tumour types." (PMID 20591152, 2010). "In the Malmö-CC cohort, we found decreased protein expression of WNT5A in colon cancer tissue in comparison with noncancer colon mucosa, whereas in the same samples, we observed increased LGR5 protein expression." (PMID 37998393, 2023). "Opinion is divided over the importance of WNT5A—an essential protein of the non-canonical Wnt/β-catenin signalling pathway—in colon cancer." (PMID 35155186, 2021). "However, a previous study in colon cancer showed that restoration of the tumour suppressor ROR2 impaired tumour growth through inhibition of β-catenin-dependent Wnt signalling, in a Wnt5a independent manner." (PMID 33494187, 2021). "We further showed that Wnt5a/b as non-canonical ligands were responsible for regulation of these target genes in colon cancer cells." (PMID 29453334, 2018). "Interestingly, the results of a recent study showed that WNT5A activates 15-PGDH via a JNK/AP-1-dependent pathway and induces the differentiation of colon cancer cells." (PMID 28402256, 2017). "Wnt2 and Wnt5a expression are also elevated in colon cancer compared to normal colon and during the progression from adenoma to carcinoma." (PMID 28147310, 2017). "Furthermore, Wnt5A and its receptor, ROR2, were found to upregulate AKT/PKB survival signaling in histone deacetylase inhibitor-resistant colon cancer." (PMID 25401518, 2014). "The expression of Wnt5a was decreased in the highly metastatic SW620 human colon cancer cell line as compared with the nonmetastatic SW480 human colon cancer cell line." (PMID 24944588, 2014). "Our data thus suggest that the canonical Wnt-dependent role of ROR2 hypermethylation in colon cancer cells does not necessarily require WNT5A." (PMID 20591152, 2010). "However, equivalent treatment did not significantly alter the migration in the Wnt5a-expressing Caco-2 colon cancer cell line." (PMID 24944588, 2014).
colon carcinoma (continued). "Increasing or decreasing extracellular WNT5A levels had little impact on β-catenin nuclear location and β-catenin/TCF-dependent transcription, suggesting that the canonical Wnt-dependent role of ROR2 epigenetic deregulation in DLD1 colon cancer cells does not necessarily require WNT5A." (PMID 20591152, 2010). "Using the prototype non-canonical ligand, Wnt5a, in comparison with Wnt3a, the prototype of a canonical β-catenin activating ligand, we describe here that non-canonical Wnt/Ca2+ cascade plays an essential role in inducing and maintaining the self-renewal capacity of colon cancer stem cells." (PMID 36969011, 2023). "Indeed, recently it has been reported that using Wnt3a and Wnt5a as prototype ligands to activate the canonical or the non-canonical pathways, respectively, promotes sphere-formation capacity and proliferation through the β-catenin-independent manner in colon cancer cells." (PMID 37804416, 2024). "In this study, we explored a possible relationship between the expression of WNT5A, a favorable prognostic factor in colon cancer, and the β-catenin signaling modulators LGR5 and RSPO3, which are also negative prognostic factors in colon cancer." (PMID 37998393, 2023). "In colon cancer cells, CASR activation stimulates secretion of WNT5A in the noncanonical Wnt signaling pathway." (PMID 37377737, 2023). "Based on these results, we next performed an analysis and found a strong negative correlation (R = −0.56) between WNT5A and DCLK1 gene transcript expression in the GSE44076 colon cancer cohort." (PMID 37998393, 2023). "WNT5A (ligand of non-canonical WNT signaling) and its mimicking peptide Foxy5 impair β-catenin signaling in colon cancer cells via unknown mechanisms." (PMID 37998393, 2023). "As WNT5A might have canonical and non-canonical effects, WNT5A/ROR2 could have a role in colon cancer through non-canonical Wnt signalling within certain molecular contexts." (PMID 20591152, 2010). "In the present study, we found a strong negative correlation between WNT5A and VEGFA expression in a colon cancer cohort (GSE44076) and that Foxy5 induced a limited (approximately 40%) downregulation of VEGFA expression in colon cancer cells and in colon cancer tissue." (PMID 37998393, 2023). "Additional studies with the human colon cancer cells SW620, and the derived from them SW620R cells, that grow at 3 mM butyrate, indicated that these cells do not express detectable levels of ROR2 (data not shown); however, they express WNT5A, and exposure to butyrate increases pAKT levels." (PMID 22073312, 2011).
ovarian carcinoma (50 papers, 2013 to 2026). A malignant neoplasm originating from the surface ovarian epithelium. "Lastly, Wnt5A was implicated in activating human primary omental mesothelial cells and subsequent invasion of ovarian cancer cells." (PMID 35053353, 2022). "Indeed, Wnt5a and other constituents of the Wnt pathway have been suggested as promising therapeutic targets in ovarian cancer, as activation of this pathway has been linked to the progression of the disease." (PMID 35628603, 2022). "In summary, we hypothesize here, that Wnt5A/FZD-5 signaling modulate αv integrin expression levels that could be associated with ovarian cancer cell proliferation, migration, and fibronectin attachment." (PMID 33723319, 2021). "Knowing that the blockage of ROR2 expression by using an anti-human antibody caused an 80% decrease in the migration of Wnt5A-transfected cells, it may be suspected that in the case of ovarian cancer, bacterial cell wall fragments may have anti-metastatic potential." (PMID 37608943, 2023). "Host-derived Wnt5a, secreted by peritoneal mesothelial cells and adipocytes within the ovarian cancer microenvironment, plays a critical role in promoting ovarian cancer metastasis." (PMID 40330466, 2025). "High levels of Wnt5a in ascites fluid enhance the adhesion, migration, and invasion of ovarian cancer cells, driving their colonization of the peritoneum." (PMID 40330466, 2025). "The Wnt5a potentially boosts VM formation in epithelial ovarian cancer through the PKCalpha mechanism." (PMID 40497987, 2025). "In ex vivo experiments, ovarian cancer cell lines acquire greater adhesion and migration ability under the influence of recombinant wnt5a." (PMID 37605299, 2023). "High CAM-derived WNT5A levels in ascites fluid have been shown to strongly increase the metastatic potential of ovarian cancer cells by activating its downstream effector Src family kinase Fgr." (PMID 37566084, 2023). "Recently we reported that Wnt5A induced integrin αv expression in ovarian cancer cells and showed a positive relationship between Wnt5A, αv, and β6 expression in the metastatic human serous ovarian cancer specimens." (PMID 35053353, 2022). "This study is the first evidence to show that Wnt5A is required for TGFβ1-induced EMT in ovarian cancer." (PMID 35053353, 2022). "Wnt5a, which belongs to the Wnt family, is the main regulator of intraperitoneal metastasis and dissemination of ovarian cancer." (PMID 35281796, 2022). "While both WNT5B and WNT5A have been shown to be expressed in ovarian cancer, their functions are distinct." (PMID 34017835, 2021). "While not much is known about the clinical implications of WNT5B, high expression of WNT5A has been significantly correlated with ovarian cancer stage, poorer overall survival and poorer progression-free survival." (PMID 34017835, 2021). "Our results with human specimens partially support our data from in vitro experiments and suggest that Wnt5A in ovarian cancer exerts a modulatory role on integrin expression." (PMID 33723319, 2021). "ILK silencing has also been shown to reduce the expression of wnt ligands (wnt3a, wnt4, and wnt5a) and β-catenin in epithelial ovarian cancer cells." (PMID 33256002, 2020). "The methylation status of Wnt5a in the human epithelial ovarian cancer cell line SKOV3 was determined by MSP analysis." (PMID 30079293, 2018). "In the current study, the role of abnormal methylation of Wnt5a gene promoter regions in human epithelial ovarian cancer was investigated." (PMID 30079293, 2018). "This is consistent with our experimental results, supporting the possible tumor suppressor gene characteristics of Wnt5a in ovarian cancer." (PMID 30079293, 2018). "In summary, Wnt5a gene region promoter aberrant methylation existed in epithelial ovarian cancer tissue, which is one of the important mechanisms of Wnt5a gene inactivation." (PMID 30079293, 2018).